C17orf67 (chromosome 17 open reading frame 67)
Tractability: Antibody: UniProt places it where antibodies can reach, with high confidence; UniProt predicts a signal peptide or a membrane-spanning region; its Gene Ontology location is reachable by antibodies, with medium confidence.
Gene: Protein-coding gene on chromosome 17 (56,791,913 to 56,838,773, reverse strand). Ensembl gene ENSG00000214226.
Subcellular location: Secreted
Gene Ontology:
Molecular function: protein binding
Cellular component: extracellular region
Genetic constraint (gnomAD): Loss-of-function variants: 12 observed, 11.33 expected, observed/expected ratio (o/e) 1.06, 90% interval 0.68 to 1.68. The upper end of that interval is the gene's LOEUF score, 1.68, which puts it in group 6 of 6, group 1 being the genes least tolerant of losing a copy. Missense variants: 115 observed, 119.12 expected, observed/expected ratio (o/e) 0.97, 90% interval 0.83 to 1.13. Synonymous variants: 59 observed, 48.97 expected, observed/expected ratio (o/e) 1.2, 90% interval 0.98 to 1.5.
Homologues: Orthologues: chimpanzee C17H17orf67 (97% identical), macaque C16H17orf67 (97% identical), dog C17orf67 (87% identical), pig C17orf67 (87% identical), rat C10h17orf67 (87% identical), mouse Gm525 (84% identical), guinea pig C17orf67 (79% identical), rabbit C17orf67 (78% identical), tropical clawed frog c10h17orf67 (60% identical), zebrafish si:dkey-31g6.6 (51% identical).
Diseases named in the same sentence as C17orf67 in open-access papers:
C17orf67 is named in the same sentence as 7 diseases in open-access papers, as found by Europe PMC text mining. Sharing a sentence is not in itself a finding about the gene and the disease. The quoted sentences say what the papers report.
metastatic tumors (1 paper, 2023). "In general, overexpression of the C4orf46, C9orf40, C17orf67 and C21orf58 gene of thymoma correlates with tumor immune cell infiltration and gene expression levels of C1orf162, C16orf54 and CXorf21 correlate with immune cell infiltration in many primary and metastatic tumors." (PMID 37373333, 2023).
C17orf67 also shares sentences with these, for which no sentence is quoted: atypical hemolytic-uremic syndrome (1 paper); microangiopathic hemolytic anemia (1); renal failure (1); Thrombocytopenia (1); thymoma (1); tumor (1).